EPCAM (epithelial cell adhesion molecule)
Diseases named in the same sentence as EPCAM in open-access papers (continued):
Sharing a sentence is not in itself a finding about the gene and the disease.
gastric cancer (continued). "We analyze the relationship between the expression of EPCAM/L1CAM and the prognosis of patients with gastric cancer according to Lauren classification." (PMID 24422715, 2013). "To avoid biasing the prognostic value of EPCAM/L1CAM by tumor stage, we analyzed the relationship between expression of EPCAM/L1CAM and prognosis of patients with gastric cancer according to TNM stage." (PMID 24422715, 2013). "We therefore analyzed the relationship between expression of EPCAM/L1CAM and prognosis of patients with gastric cancer according to regional lymph nodes." (PMID 24422715, 2013). "Three hundred and sixteen gastric cancer cases had low expression of both L1CAM and EPCAM; 125 gastric cancer cases had high expression of both L1CAM and EPCAM." (PMID 24422715, 2013). "As TNM stage, lymph node and distant metastasis are used as prognostic factors for gastric cancer, we further analyzed the correlation between L1CAM/EPCAM expression and patient prognosis according to Lauren classification, TNM stage and regional lymph nodes." (PMID 24422715, 2013). "Our study suggests that overexpression of EPCAM and L1CAM is common in gastric cancer, and plays an important role in the progression and metastasis of gastric cancer." (PMID 24422715, 2013). "The current study examined expression of L1CAM and EPCAM in surgical specimens of gastric carcinoma, to explore possible correlations between L1CAM and EPCAM expression and clinicopathological variables and prognosis." (PMID 24422715, 2013). "The seven RNAs upregulated in gastric cancer were CLDN18, EPCAM, REG4, BBC3, OLFM4, PPARG, and CDH17, while the two downregulated genes were IFITM1 and HIF1A." (PMID 22929309, 2012). "The method reported a LOD of 2.15 × 106 particles/μL using MUC1 probe for gastric cancer cell line HGC-27-derived EV sample, as well as validation for other gastric cancer biomarkers (EpCAM, PTK7, PD-L1) for both cell line EV isolates and human plasma specimens." (PMID 41404198, 2025). "In addition, CPT1C promotes gastric cancer drug resistance by enhancing FAO and subsequently upregulating the mRNA expression levels of gastric cancer stem cell markers (CD44, EpCam, and Lgr5)." (PMID 41219902, 2025). "Other targets that entered clinical trials of gastric cancer primarily included HER2 (NCT04660929), CEA (NCT05396300), MUC1 (NCT05239143), EpCAM (NCT05028933, NCT03563326), MSLN (NCT03941626), EGFR (NCT03740256), B7H3 (NCT04864821) and NKG2DL (NCT04550663), with no conclusions reported yet." (PMID 38622705, 2024). "Endogenous BAP31 and EpCAM were coimmunoprecipitated from the lysate of the gastric cancer cell line MKN-45 in the hydrophobic surfactant Nonidet P 40 (NP40)." (PMID 37834237, 2023). "Interrogation of CCLE database revealed that FZD5 is positively correlated with epithelial-related factors CDH1 (E-cadherin), OCLN (Occludin), EPCAM and ELF3, while negatively correlated with mesenchymal-related factors VIM (Vimentin), SNAI2 (Slug), ZEB1 and ZEB2 in 37 gastric cancer cell lines." (PMID 33618713, 2021). "Several molecular targets were previously used to detect CTCs/DTCs in patients with gastric cancer, including CEA, mucin 1, c-Met, human telomerase reverse transcriptase (hTERT), epithelial cell adhesion molecule (EpCAM), survivin, and matrix metalloproteinase-1 (MMP-1)." (PMID 30056567, 2019). "Multi-color immunofluorescence analyses of EpCAM, vimentin, and DAPI were performed by measuring the fluorescence intensities of respective target molecules in 3D-cultured human gastric cancer cell-lines (AGS, KATOIII, NCI-N87, MKN-45, and SNU-216) on a micropillar chip." (PMID 31850215, 2019). "The specificity and binding affinity of the RNA aptamer was assessed against live human cancer cell lines expressing EpCAM and those that did not express EpCAM (breast, colorectal and gastric cancers) and analysed using flow cytometry." (PMID 30586898, 2018).
gastric cancer (continued). "Although many basic and clinical studies have explored the relationship between EpCAM and gastric cancer, these studies have not reached a consensus." (PMID 28403178, 2017). "Comparing to conventional EpCAM/CKs-dependent strategy, SE-iFISH® demonstrated higher sensitivity for CTC detection, showing 90.5 % positive rate of SE-iFISH® vs 54.8 % of CellSearch on the identical population of gastric cancer patients." (PMID 26718583, 2015). "We observed EpCAM expression in most of the gastric cancers, while it was absent in normal gastric epithelia." (PMID 23830302, 2013). "EpCAM is usually not expressed in healthy gastric mucosa but its de novo expression occurs frequently in gastric cancer." (PMID 23830302, 2013). "Absence of EpCAM was observed in 37 gastric cancer cases (23%)." (PMID 23830302, 2013). "Gastric cancer stem-like cells (GCSCs) have recently been reported in GC cell lines and primary tumors with the markers CD71–, EpCAM+/ CD44+ and CD90+ identifying them." (PMID 23554769, 2012). "The murine gastric carcinoma cell lines as well as the primary gastric carcinomas mimic closely human gastric carcinomas and derived cell lines in expressing CEA (when established from tumor-bearing CEA-transgenic mice), upregulate CEACAM1, downregulate E-cadherin expression and express EpCAM." (PMID 16536871, 2006). "However, this method using anti-EpCAM-coated magnetic beads to capture markers absent from leukocytes has considerable limitations in detecting EMT CTCs, which have been proven to be linked to a worse treatment response in gastric cancer patients by our previous study." (PMID 36474175, 2022). "EpCAM is commonly expressed in gastric cancer, with one study demonstrating CSC characteristics within the EpCAM+ tumour population, but not in EpCAM- tumour cells." (PMID 33628765, 2021). "Previously, gastric TICs have been identified by using CD44, CD44 and EpCAM, CD44 and CD24, CD44 and CD54, CD90, and aldehyde dehydrogenase 1 as markers, but CD49f has not been used to detect TICs in gastric cancers." (PMID 24015244, 2013). "In order to better identify gastric cancer patients with EMT, EMT and non-EMT patients were distinguished by combining the expression levels of VIM (high expression), CDH1 (low expression), S100A4 (high expression) and EPCAM (low expression)." (PMID 33535187, 2021).
melanoma (74 papers, 2009 to 2025). A malignant, usually aggressive tumor composed of atypical, neoplastic melanocytes. "When implanted in thymectomized mHM, which were subsequently engrafted with patient melanoma tissue (autologous, or mHMTA), sTOs expressed thymic tissue markers EPCAM, KRT5, and KRT8 and contained developing double-positive T cells." (PMID 41129601, 2025). "We have focused our attention on the epithelial markers EpCAM and its homolog Trop2 and the marker of highly progressive melanoma stem cells, CD27145,46." (PMID 38570556, 2024). "Our result demonstrated CAR-T cell-specific activity reflected by the elevation of both interferon-gamma and Granzyme B in EpCAM+ gastric-PDXO-GA0091 co-culture as compared to the EpCAM- melanoma PDXO-ME1154 co-culture." (PMID 36602988, 2023). "In the second experiment, we tested EpCAM-CAR-T cells co-cultured with EpCAM+ gastric PDXO-GA0091 and EpCAM- melanoma PDXO-ME1154, and measured the interferon-gamma and Granzyme B levels in the culture." (PMID 36602988, 2023). "The notion that bispecific antibodies harbor the potential to induce long-term immunological protection in addition to acute tumor cell lysis has been exemplified in a murine model of EpCAM-positive melanoma." (PMID 32438548, 2020). "To date, numerous preclinical studies have evaluated CAR-modified γδ T cells targeting neuroblastoma, melanoma, B cell malignancies, and epithelial cell adhesion molecule (epCAM)-positive adenocarcinomas." (PMID 31884955, 2019). "Associations have been established between EpCAM marker-positive CTC counts and overall survival in other malignancies and between CD146 melanoma-marker positive CMC counts and survival in melanoma." (PMID 24811334, 2014). "Remarkably, almost all cell lines (except of melanoma cell lines) of the different entities had similar levels of EpCAM protein, although they exhibited different mRNA expression levels." (PMID 22590529, 2012). "In comparison with the high-affinity EpCAM-specific surrogate antibody BiLu (~109 M-1), which was evaluated in a similar melanoma model, the required therapeutic dosage is about 15–30 times higher." (PMID 23134699, 2012). "The remaining material was stained with the epithelial markers EpCAM and cytokeratin (CK) 7/8 or for the melanoma marker HMW-MAA/MCSP." (PMID 21595914, 2011). "However, the CellSearch platform has limited utility: detection is restricted to CSF-TCs expressing epithelial cell adhesion molecule (EpCAM) and is therefore applicable only to patients with melanoma LMD." (PMID 38826788, 2024). "Nevertheless, tumors could be characterized by low EpCAM expression or be EpCAM-negative, as in the case of malignant melanoma and medulloblastoma." (PMID 36674455, 2023). "As epithelial tumor cells can lose EpCAM expression due to the transition to mesenchymal subtype and HMW-MAA/MCSP expression on melanoma cells is only found in 85%, both EpCAM and HMW-MAA/MCSP assays could fail in detecting CTCs." (PMID 34207653, 2021). "Indeed, treatment with EpCAM/CD3-bAb in a murine melanoma model resulted in upregulation of the immune checkpoint molecule CTLA-4 on recruited T cells in vivo and CTLA-4 blockade enhanced the humoral antimelanoma response with moderate survival benefit." (PMID 32438548, 2020). "Indeed, given the difficulty of isolating whole CMCs, MCAM/MUC18/MelCAM/CD146 has been proposed as a substitute for EpCAM in immuno-targeting and separation of melanoma cells using positive selection." (PMID 28280601, 2017). "Indeed, CD146 has been proposed as a substitute for EpCAM in immunomagnetic targeting and separation of melanoma cells using positive selection." (PMID 24811334, 2014). "Also EpCAM protein immunoreactivity was below detection limits in the melanoma cell lines in vitro and in vivo." (PMID 22590529, 2012). "Except for melanoma, all cell lines expressed EpCAM mRNA and protein when grown in vitro." (PMID 22590529, 2012).
melanoma (continued). "Additionally, the intratumoral injection of GD2 or epithelial cell adhesion molecule (EpCAM)-targeting IL-2 immunocytokines increased the anti-tumor effect and immune cell presence in neuroblastoma and melanoma in vivo compared to intravenous administration and unconjugated IL-2." (PMID 33803078, 2021). "In our recently published work, we screened several melanoma and carcinoma cell lines (MV3, SCL‐1, SCL‐2, BLM, patient‐derived HNC cells) and targets (MCSP, EpCAM, cell surface vimentin) to find a suitable candidate for the testing of microfluidic platforms." (PMID 35573135, 2022). "MTFs were readily identifiable in primary melanomas, with strong staining for melanocyte (MLANA and ALCAM), macrophage (CD204, CD206), and epithelial (pan-KRT, EpCAM) markers." (PMID 26267609, 2015). "In melanoma, these challenges increase as standard CTC markers like EpCAM [commonly used in detecting CTCs in epithelial cancers such as breast and prostate] are often absent in melanoma CTCs." (PMID 39766118, 2024). "Unlike other solid tumors, such as adenocarcinomas of the colon and pancreas and hormone-refractory adenocarcinomas of the prostate, melanoma has non-high levels of EPCAM protein." (PMID 36835424, 2023). "As far as detection is concerned, widely used strategies based on the use of EpCAM (epithelial cell adhesion molecule) and other epithelial markers are not useful in this context, as their expression does not occur in melanoma cells." (PMID 34575876, 2021). "Melanoma cells do not express epithelial cell adhesion molecule (EpCAM), the classical epithelial cell surface marker that is at the basis of most CTC isolation strategies." (PMID 32295074, 2020). "EpCAM has a high expression in nearly all epithelial tumor types, while tumors of mesenchymal lineage such as melanomas and sarcomas have no expression." (PMID 32923313, 2020). "Following in vitro verification using Lewis lung carcinoma (LLC1) (EpCAM-positive) and B16F10 (EpCAM-negative) melanoma cells, syngeneic tumor models were used to evaluate specificity and sensitivity of the surface charged nanoparticles." (PMID 32923313, 2020). "In contrast, the majority of squamous cell carcinomas show lower EpCAM expression than adenocarcinomas and EpCAM was found to be absent in sarcomas, lymphomas, melanomas, and neurogenic tumors." (PMID 31225512, 2019). "Heterogeneities in the expression pattern of mHsp70 and EpCAM were also observed for human lung (EPLC-272-H, H1339, A549), melanoma (LS174T), pancreatic (PANC-1, MIA PaCa-2), cervix (HeLa), colon (HCT-15), brain (LN-229, U-87), and head and neck (UP154, UD5) cancer cell lines." (PMID 30443493, 2018). "Melanoma does not express the classical epithelial cell surface marker EpCAM, which has formed its basis for most CTC isolation, and is the only Food and Drug Administration-approved platform for the prognosis of this kind of carcinoma." (PMID 28280601, 2017). "Further, similarly to melanoma and unlike many epithelial cancer types, CNS malignancies do not express EpCAM, a marker that is commonly used for CTC detection." (PMID 27843628, 2016). "They stained for standard epithelial markers including pan-cytokeratins (pan-KRTs) and EpCAM (even though melanomas are not derived from epithelium, they routinely express epithelial markers)." (PMID 26267609, 2015). "In the case of SK-Mel-28 melanoma cells that do not express EpCAM, the recovery rate with SE was 70%, whereas no cell was isolated with anti-EpCAM strategy." (PMID 26267323, 2015). "In all primary melanomas, we routinely observed many apparent MTFs, which stained for macrophage (pan- and M2-polarization) markers, as well as for melanocyte-specific (MLANA) and epithelial (EpCAM and pan-KRT) markers." (PMID 26267609, 2015). "While EpCAM is the most commonly chosen antibody for CTC capture, it is not highly expressed on all epithelial cancers and can not be used to recover cells from non epithelial cancers such as melanoma." (PMID 24489774, 2014).
melanoma (continued). "Unlike other solid tumors, melanoma has non-high levels of EPCAM protein." (PMID 36835424, 2023). "It is widely known that melanoma cells do not express EpCAM." (PMID 37511550, 2023). "Because, EpCAM antigen is not expressed by all tumors, we divided malignant patients into two groups according to their etiology: 1) carcinoma (n = 44) known to generally express EpCAM, and 2) non-carcinoma (n = 27, mesothelioma, melanoma, lymphoma and sarcoma) generally not expressing EpCAM." (PMID 26689993, 2016). "Moreover, differential expression of melanoma epithelial cell adhesion molecule (MCAM) by other non-melanoma cells such as vascular endothelial cells, smooth muscle cells and pericytes makes it less reliable for melanoma cell isolation." (PMID 26815318, 2016). "Although EpCAM is expressed on many types of epithelial tumor cells, it is highly heterogeneously and dynamically expressed or even absent on cells of several types of cancer, such as melanoma, glioma and mesenchymal tumors." (PMID 26267323, 2015). "In a cohort of samples from patients with advanced melanoma (a tumor of non-epithelial origin and therefore in which EpCAM-based cell selection is not useful), these investigators were able to analyze the transcriptome from single CTCs expressing melanoma markers." (PMID 25222379, 2014). "However, EpCAM capture technologies are of limited utility for non-epithelial cancers such as melanoma." (PMID 24811334, 2014). "Our analysis of MEWO and FemX-1 cell lines that are both derived from melanoma revealed that no EpCAM mRNA expression could be detected." (PMID 22590529, 2012). "To determine whether LCs respond to melanoma growth in the epidermis, we established a clinically relevant syngeneicinjectable murine melanoma model using the YUMM1.7(BrafV600E/WTCdkn2a−/− Pten−/−) cell line and measured the frequency of epidermal LCs [CD11b+MHCII+CD24+EpCam+ cells; fig." (PMID 37043573, 2023). "However, most circulating melanoma cells (CMCs) do not express EpCAM." (PMID 24811334, 2014). "Defining CTCs in epithelial cancer patients as CD45- CK+ and/or EpCAM+, the detection rate increased to 73% (61/84), and the median count of these cells was 8 (range: 1-105)/10 mL blood, which did not significantly differ anymore from the median count of melanoma cells (p = 0.418)." (PMID 21595914, 2011). "The melanomas with brain metastases (BM) showed higher expression of CTLA-4, and lower expression of 4-1BB, CD163, GITR, IDO1, PR, EPCAM and ER-alpha than the melanomas without metastases." (PMID 40621453, 2025). "Since melanoma is not an epithelial cancer, CTCs are extraordinarily hard to isolate from the blood of patients, because they do not express common CTC markers such as EpCAM or epithelial cytokeratins that would distinguish them from normal blood cells." (PMID 27843628, 2016). "Because melanoma is derived from neural crest cells and thus often exhibits mesenchymal features, conventional CTC detection platforms designed for epithelial cancers using cell surface markers (such as epithelial cell adhesion molecule, EpCAM) may not be optimal for patients with melanoma." (PMID 25807549, 2015).